TGFBR1 (transforming growth factor beta receptor 1)
Diseases named in the same sentence as TGFBR1 in open-access papers (continued):
Sharing a sentence is not in itself a finding about the gene and the disease.
cyst (4 papers, 2011 to 2023). A sac-like closed membranous structure that may be empty or contain fluid or amorphous material. "By 8 months of age, the uterine pathology in the Tgfbr1 cKO mice culminated in uterine cyst formation and an almost unrecognizable mass of tissue." (PMID 22028666, 2011).
endothelial dysfunction (4 papers, 2009 to 2022). In vascular diseases, endothelial dysfunction is a systemic pathological state of the endothelium (the inner lining of blood vessels) and can be broadly defined as an imbalance between vasodilating and vasoconstricting substances produced by (or acting on) the endothelium. "The second network proposed the interaction of beta-catenin with CDH5 and TGFBR1 through Smad molecules to contribute to endothelial dysfunction, often a precursor of CVD." (PMID 24465431, 2014). "(d) Lastly, from our fourth network we have inferred that the interaction of β-catenin with CDH5 and TGFBR1 through Smad molecules could contribute to endothelial dysfunction." (PMID 19997558, 2009).
granulosa cell tumor (4 papers, 2016 to 2023). A slow-growing, malignant tumor, characterize by the presence of granulosa-like cells and Call-Exner bodies, that is almost always found in the ovary. "Finally, we compared the differentially expressed genes (DEGs) in our model with the published dataset for TGFBR1-CA ovaries, a mouse model of granulosa cell tumors caused by constitutively active TGFβ signaling." (PMID 36430923, 2022). "Our previous study has shown that sustained activation of TGFβ receptor 1 (TGFBR1) driven by anti-Mullerian hormone receptor type 2 (Amhr2)-Cre in the mouse testis induces the formation of testicular granulosa cell tumors (TGCTs)." (PMID 38067144, 2023). "Both females and males harboring Amhr2-Cre mediated overactivation of TGFBR1 develop gonadal tumors reminiscent of granulosa cell tumors revealed by both histological and molecular characterizations." (PMID 38067144, 2023). "A histological analysis showed that Sertoli cell-specific activation of TGFBR1 led to the development of neoplasms resembling granulosa cell tumors, which derailed spermatogenesis." (PMID 38067144, 2023). "Moreover, since it is a very strong oncogene, TGFBR1 promoted granulosa cell tumour development in mice." (PMID 30382374, 2019). "Thus, future studies are needed to test the effect of TGFBR1 modulators on the cellular properties and the development of human granulosa cell tumors, as may yield novel insights into the treatment of these tumors." (PMID 27344183, 2016). "Because granulosa cells may transdifferentiate into Sertoli cells in granulosa cell tumors, we assessed whether there were Sertoli cell-like components in the TGFBR1-CAAcre model by immunofluorescence using an antibody directed to SRY (sex determining region Y)-box 9 (SOX9), a Sertoli cell marker." (PMID 27344183, 2016). "To determine the relevance of TGFBR1-CAAcre mice as a potential model for granulosa cell tumors, we measured serum estradiol (E2), inhibin B, inhibin A, and follicle-stimulating hormone (FSH) levels in control and TGFBR1-CAAcre mice." (PMID 27344183, 2016). "We found that ovarian tumors from TGFBR1-CAAcre mice were immunoreactive for FOXL2, FOXO1, and INHA, supporting the development of granulosa cell tumors in these mice." (PMID 27344183, 2016). "However, a limitation of our model is that dysregulation of TGFβ signaling in granulosa cell tumors does not necessarily result from overactivation of TGFBR1." (PMID 38067144, 2023).
lung adenocarcinoma (4 papers, 2014 to 2023). A carcinoma that arises from the lung and is characterized by the presence of malignant glandular epithelial cells. "LINC02323 sponged miR-1343-3p to upregulate the TGFBR1 expression and promote the epithelial-mesenchymal transition and metastasis in lung adenocarcinoma." (PMID 35047414, 2021). "In summary, the microRNA, miR-133a, inhibits the expression levels of multiple oncogenic receptors, i.e., EGFR, IGF1R, and TGFBR1, and mediates cell growth and invasion in lung adenocarcinoma." (PMID 24816813, 2014).
malignant glioma (4 papers, 2014 to 2025). A grade III or grade IV glioma arising from the central nervous system. "TGF-β1, along with TGFBR1/2, shows expression only in malignant gliomas and is not expressed in normal brain tissues, gliosis, or low-grade astrocytomas." (PMID 40335825, 2025).
ovarian tumor (4 papers, 2016 to 2018). "A somewhat unexpected finding was that activation of TGFBR1 using inducible Gli1-Cre caused ovarian tumor formation." (PMID 27344183, 2016). "In an effort to define the role of aberrant activation of TGFB signaling in the pathogenesis of ovarian tumors, we utilized a mouse model harboring constitutively active TGFBR1." (PMID 29221447, 2017). "To define the molecular characteristics of ovarian tumors in TGFBR1-CAG9Cre mice, we performed immunostaining to examine the expression of a granulosa cell lineage marker FOXL2 and three other granulosa cell-expressed proteins, FOXO1, INHA, and AMH." (PMID 29221447, 2017). "The development of GCTs in TGFBR1-CAG9Cre mice begs the question of how overactivation of TGFBR1 links to ovarian tumor formation." (PMID 29221447, 2017). "Remarkably, we found the development of gross ovarian tumors in TGFBR1-CAG9Cre mice at the age of 2-3 months." (PMID 29221447, 2017). "Results from the TGFBR1-CACcre mice demonstrated that overactivation of TGFBR1 in granulosa cells led to ovarian tumor development." (PMID 27344183, 2016). "Generation of constitutively active TGFBR1 in the mouse ovary using Cyp19-Cre reproduced ovarian tumor phenotype, which corroborated findings from studies using Amhr2-Cre." (PMID 27344183, 2016). "Unexpectedly, we found that constitutive activation of TGFBR1 using GLI-Kruppel family member GLI1 (Gli1)-CreERT2 (designated as TGFBR1-CAGcre) caused the development of INHA-positive ovarian tumors following tamoxifen injection." (PMID 27344183, 2016). "It is interesting to note the focal expression of KRT8 in late-stage ovarian tumors in both TGFBR1-CACcre and TGFBR1-CAAcre mice." (PMID 27344183, 2016). "The localization of FOXL2, INHA, FOXO1, AMH, and DDX4 was detected in the granulosa cell or oocyte compartment of control ovaries, while ovarian tumor tissues from TGFBR1-CAG9Cre mice were immunoreactive with FOXL2, INHA, and FOXO1, supporting the development of GCTs in these mice." (PMID 29221447, 2017). "Strikingly, gross ovarian tumors were prominent in TGFBR1-CAAcre mice examined at 2 months of age." (PMID 27344183, 2016). "Second, ovarian tumors in TGFBR1-CAAcre mice had higher levels of Gli1 and Gli2 mRNAs." (PMID 27344183, 2016). "Nevertheless, the complementary mouse models created by the current study, particularly the TGFBR1-CACcre models, are valuable in future studies to define genes/pathways that are related to granulosa cell specific activation of TGFBR1 during ovarian tumor initiation and progression." (PMID 27344183, 2016). "Further histochemical and molecular analyses provided evidence of overactivation of TGFBR1 in the granulosa cell compartment during ovarian pathogenesis in TGFBR1-CAG9Cre mice, along with upregulation of Gli1 and Gli2 and downregulation of Tgfbr3 in ovarian tumor tissues." (PMID 29221447, 2017).
squamous cell carcinoma (4 papers, 2015 to 2024). A carcinoma arising from squamous epithelial cells. "TGFBR1 null mutations cause multiple self‐healing squamous epithelioma (MSSE), while deletion of TGFBR1 in mice promotes squamous carcinoma." (PMID 31475485, 2019). "Tgfbr1 and Pten were able to inhibit the expression of NLRP3, ASC, caspase-1, IL-1β, and IL-18 in a mouse squamous cell carcinoma of the head and neck model." (PMID 32723297, 2020). "To determine whether over-expression of AGR2 was related to high-grade squamous cell carcinoma in mice, we performed AGR2 immunohistochemistry and found that AGR2 was located mostly in the membrane and cytoplasm of the cancer cell of Tgfbr1 cKO mice and Tgfbr1/Pten 2cKO mice (n = 5, respectively)." (PMID 25871396, 2015).
thyroid cancer (4 papers, 2019 to 2025). "Further exploration of the consistently modulated genes, particularly FN1, PIK3R1, and TGFBR1, may reveal new molecular insights and therapeutic targets for managing aggressive thyroid cancers." (PMID 40650218, 2025). "Analysis from the online site UALCAN displayed that KRT80 was a positive correlation with TGFBR1 in adrenocortical carcinoma (ACC), kidney renal papillary cell carcinoma (KIRP), and thyroid carcinoma (THCA), and their Pearson Correlation Coefficient was 0.37, 0.34, and 0.3." (PMID 36248424, 2022).
Alzheimer disease (3 papers, 2020 to 2024). A progressive, neurodegenerative disease characterized by loss of function and death of nerve cells in several areas of the brain leading to loss of cognitive function such as memory and language. "Genes that were both selective for and highly expressed in the microglial cluster were Tgfbr1, Cyth4, Ikzf1, Dock2, and Inpp5d, many of which are associated with Alzheimer’s Disease (AD)." (PMID 38263132, 2024).
aneurysmal disease (3 papers, 2014 to 2022). "To address this apparent paradox and to gain more insight into the pathophysiology of aneurysmal disease, we characterized a new Tgfbr1 mouse model carrying a p.Y378* nonsense mutation." (PMID 24587008, 2014). "It was reported that heterozygous kinase-inactivating mutations in genes coding for either transforming growth factor-β receptor subunit (TGFBR1 or TGFBR2) cause Loeys–Dietz syndrome, characterized by a highly penetrant and aggressive aneurysmal disease." (PMID 31045834, 2019).
Cirrhosis (3 papers, 2013 to 2025). A chronic disorder of the liver in which liver tissue becomes scarred and is partially replaced by regenerative nodules and fibrotic tissue resulting in loss of liver function. "HCC tissue had a significantly reduced TGFBR1 H-score compared to TAT (p = 9.6 × 10−9) or cirrhosis-only tissue (p = 0.013)." (PMID 35677836, 2022). "Based on these results, we tested H- scores for TGFBR1 ranging from 140 to 200 as thresholds for predicting cirrhosis only versus HCC and we tested H-scores ranging from 114 to 145 as TGFBR2 H-score thresholds." (PMID 35677836, 2022). "The reduced staining of TGFBR1 in HCC tissue was significant compared with that in TAT (p = 0.0013) or compared with that in cirrhosis-only tissue (p = 2.4 × 10−7)." (PMID 35677836, 2022). "In this study, we used immunohistochemical analysis to explore the diagnostic potential of TGFBR1 and TGFBR2 as biomarkers to differentiate HCC from cirrhosis." (PMID 35677836, 2022). "IHC staining intensities for TGFBR1 and TGFBR2 were lower in HCC tissue than in tumor-adjacent tissue (TAT) or in tissue from cirrhosis-only patients." (PMID 35677836, 2022). "The mean and standard deviation (SD) of the H-score for TGFBR1 in HCC tissue (n = 43) were 165.0 ± 56.6, in TAT (n = 41) were 232.9 ± 36.6, and in cirrhosis-only tissue (n = 28) were 196.1 ± 43.8." (PMID 35677836, 2022). "The mean and SD for TGFBR1 H-scores were 106.4 ± 45.1 for HCC tissue (n = 11), 173.6 ± 33.4 for TAT (n = 11), and 252.8 ± 31.7 for cirrhosis-only tissue (n = 9)." (PMID 35677836, 2022). "Next, we used multivariable logistic regression to fit a model using H-scores from both TGFBR1 and TGFBR2 scores with HCC versus cirrhosis as the dependent variable." (PMID 35677836, 2022). "We also determined that only a subset of the patient cohorts exhibited a consistent significant reduction in TGFBR1 intensity both within a patient sample in regions near tumor tissue in patients with HCC and between patients when comparing those with HCC to those with only cirrhosis." (PMID 35677836, 2022). "In contrast, the mean and SD of the AI-assigned H-scores for TGFBR1 were 209.22 ± 57.14 in HCC tissue (n = 50) and 230.28 ± 54.2 in cirrhosis-only tissue (n = 22), and this was not a significant difference (p = 0.15)." (PMID 35677836, 2022).
epilepsy (3 papers, 2018 to 2022). A brain disorder characterized by episodes of abnormally increased neuronal discharge resulting in transient episodes of sensory or motor neurological dysfunction, or psychic dysfunction. "Single nucleotide polymorphisms in TGFBR1 are associated with a risk of epilepsy in a Chinese population." (PMID 35625943, 2022). "Moreover, results of clinical observation indicated that the rs6478974 TT genotype could inhibit the susceptibility to epilepsy by reducing the levels of transforming growth factor beta receptor 1 (TGFBR1) mRNA, which is a target of let-7b." (PMID 36278003, 2022). "More specifically, the TGFBR1 AT and TT genotypes emerge as a protective factor, whereas the TCTAT and TCCAA haplotypes emerge as a risk factor for epilepsy." (PMID 35625943, 2022). "Further qRT-PCR analysis shows that TGFBR1 mRNA levels are significantly higher in epilepsy patients than in controls." (PMID 35625943, 2022).
glaucoma (3 papers, 2010 to 2025). Increased pressure in the eyeball due to obstruction of the outflow of aqueous humor. "In our analysis, TGFBR1 is associated with glaucoma, potentially establishing a causal link with GLC1J, a connection not previously reported despite the gene’s presence within the critical region." (PMID 41255976, 2025).
head and neck cancer (3 papers, 2009 to 2018). A primary or metastatic malignant neoplasm affecting the head and neck. "Our study demonstrates that the Tgfbr1/Pten 2cKO mouse model of human HNSCC is a useful model for assessing antitumor activity of new cancer therapeutic agents, and that IL-13-PE has therapeutic potential to treat human head and neck cancer." (PMID 23421960, 2013).
head and neck squamous cell carcinoma (3 papers, 2013 to 2021). A squamous cell carcinoma that arises from any of the following anatomic sites: lip and oral cavity, nasal cavity, paranasal sinuses, pharynx, larynx, and salivary glands. "We previously reported that the deletion of the TGF-β receptor I (Tgfbr1) promotes tumorigenesis of head and neck squamous cell carcinoma, mainly through the activation of the Akt pathway, but it does not initiate it." (PMID 24124460, 2013). "Moreover, TIGIT blockade presents anti-tumor efficacy in Tgfbr1/Pten2 conditional knock-out (KO) mouse model that spontaneously develops head and neck squamous cell carcinoma (HNSCC) upon tamoxifen injection." (PMID 33670993, 2021).
Infertility (3 papers, 2010 to 2022). "Two of the proteins stably interacting specifically with A189V FSHR, amyloid precursor protein (APP) and TGF-beta receptor type-1 (TGFBR1), have been indicated to have a role in gonadal development or linked to infertility." (PMID 35471239, 2022). "Further in-depth understanding of the functional and regulatory significance of TGFBR1–mediated signaling in female reproductive physiology and pathology may help to discover novel therapeutic approaches for infertility treatment." (PMID 22028666, 2011). "Copulatory plugs were found in the Tgfbr1 cKO females, indicating the infertility was not due to disrupted mating behavior." (PMID 22028666, 2011).
liver cancer (3 papers, 2020 to 2023). An epithelial or non-epithelial malignant neoplasm that arises from the liver. "TGFBR1 was mainly expressed in the cytoplasm/membrane and showed a positive expression of 54.5% in liver cancer tissues." (PMID 36901700, 2023).
Lupus (3 papers, 2021 to 2025). "Specifically, ligand–receptor pairs such as Thy1-(Itgam+Itgb2), Mif-(Cd74+Cxcr4), Tgfb1-(Tgfbr1+Tgfbr2), and Pecam1-Pecam1 showed higher mean expression levels in lupus mice than in DHA-treated mice." (PMID 40728997, 2025).
lymphoma (3 papers, 2010 to 2021). A malignant (clonal) proliferation of B- lymphocytes or T- lymphocytes which involves the lymph nodes, bone marrow and/or extranodal sites. "TCLlnc1/HNRNPD/YBX1 complex upregulated transcription of TGFB2 and TGFBR1 genes, activated the tumor growth factor-β signaling pathway, resulting in lymphoma progression, and might be a potential target in PTCL." (PMID 33767152, 2021).
neuroblastoma (3 papers, 2021 to 2023). Neuroblastoma (NB) is the most common solid, extracranial childhood tumor. "The expression of MYCN, AURKA, TGFBR1, and TGFBR2 is directly inhibited by miR-186, which can inhibit the tumorigenetic potential of neuroblastoma." (PMID 37426487, 2023). "Directly downregulates MYCN and AURKA in neuroblastoma cells, which can potentially have a negative impact on their survival; miR-186 upregulation in NK cells resulted in the downregulation of TGFBR1 and TGFBR2 and, thus, impaired the TGFβ1-dependent inhibition of NK cells’ cytotoxicity." (PMID 33530529, 2021).
Obesity (3 papers, 2017 to 2023). Accumulation of substantial excess body fat. "In addition, the expression of TGF-β receptor 1 (Tgfbr1) and Smad3 was also increased in the WAT of HFD-induced obese mice, and adipocyte-specific deletion of Tgfbr1 promoted browning and protected against obesity, glucose intolerance, and hepatic steatosis." (PMID 36674862, 2023). "Knockout of TGFBR1 promoted beige adipogenesis and protected against high-fat diet–induced obesity." (PMID 35189145, 2022).
oral squamous cell carcinoma (3 papers, 2011 to 2020). "Combined epithelial knock out of Tgfbr1 and Pten mice will full penetrated develop head neck and oral squamous cell carcinoma in a short period window (3–6 weeks after tamoxifen induction)." (PMID 26556875, 2015). "miR-142-3p (80% sEV signal), was recently shown by another group to be selectively packaged in sEVs by a panel of oral squamous cell carcinoma cell lines, which resulted in lower intra-cellular levels and promoted malignant changes in these cells via increase of TGFBR1 expression." (PMID 32350368, 2020).
pancreatic adenocarcinoma (3 papers, 2021 to 2024). "Similarly, the cytokine TGFBR1, which is associated with PD-L1 expression in pancreatic adenocarcinoma, was shown to be highly expressed in the PD-L1-H group." (PMID 35145511, 2021). "Pancreatic adenocarcinoma tumors exhibit increased levels of mRNA expression for components of the Transforming growth factor-β pathway (TGFB1/2/3, TGFBR1/2/3) and Interferon Type I pathways (IFNAR1, STAT1, IRF9 and IFI27)." (PMID 39457004, 2024).
papilloma (3 papers, 2013 to 2016). A benign epithelial neoplasm that projects above the surrounding epithelial surface and consists of villous or arborescent outgrowths of fibrovascular stroma. "Phenotypically, these lesions appeared as differentiated papillomas in Tgfbr1 wild-type and heterozygous mice." (PMID 27558455, 2016). "Previous data suggested that tumorigenesis of Tgfbr1/Pten 2cKO mice has evident papilloma stages, and high molecular expression of miR-135b regulates HIF-1α." (PMID 26872381, 2016). "Treatment with IL-13-PE was then initiated four weeks from the day tumor induction began, since papillomas and early carcinomas generally start to appear at this time in the Tgfbr1/Pten 2cKO mouse." (PMID 23421960, 2013).